TNF (tumor necrosis factor)
Diseases named in the same sentence as TNF in open-access papers (continued):
Sharing a sentence is not in itself a finding about the gene and the disease.
endothelial dysfunction (continued). "Patients with IBD have an increased production of reactive oxygen species (ROS), increased expression of inflammatory cytokines (TNF-⍺ and IL-6) and antibodies that lead to vascular smooth muscle cell proliferation (VSMC), endothelial dysfunction, and the development of CVD." (PMID 34682835, 2021). "Our model of endothelial dysfunction revealed that TNF-α-induced endothelial dysfunction did not alter NR4A2 expression." (PMID 34667209, 2021). "Recent analyses have shown that SLE-specific circulatory factors, TNF-α, interleukin-17, interferons, ligand of cluster of differentiation 40 (CD40L), and C-reactive protein (CRP), lead to endothelial dysfunction via promotion of abnormal eNOS function and enhanced oxidative stress." (PMID 32351667, 2020). "The pro-inflammatory cytokine storm, with elevated levels of interleukin-6 (IL-6), IL-2 receptor, and tumor necrosis factor (TNF)-α, could also participate in endothelial dysfunction and leukocyte recruitment in the microvasculature." (PMID 32903391, 2020). "We have not evaluated various indicators related to inflammation or endothelial dysfunction, such as TNF-a and IL-6." (PMID 32433661, 2020). "Moreover, inflammatory markers TNFα and hs-CRP together with biochemical markers of endothelial dysfunction, ICAM-1 and VCAM-1, were also stratified according to GST risk genotypes." (PMID 31275451, 2019). "TNF-α is one of the most important inflammatory mediators in endothelial cells, and a large number of studies suggest a link between TNF-α mediated inflammation damage and endothelial dysfunction." (PMID 31557846, 2019). "Inflammatory markers (TNF-α, IL-6, hsCRP) and endothelial dysfunction markers (E-selectin, ICAM-1, VCAM-1) between MetS and non-MetS patients by gender." (PMID 31550292, 2019). "In conclusion, the present study in HUVECs demonstrated that miR-21-mediated DDAH1/ADMA/NO signal pathway plays an important role in TNF-α-induced endothelial dysfunction, and DMY attenuated endothelial dysfunction induced by TNF-α in a miR-21-dependent manner." (PMID 29682517, 2018). "Its correlation with serum levels of biological markers that could participate in endothelial dysfunction pathways such as NO3−/NO2− ratio, NO2−, citrulline, TNFα, IL-1, IL-6, IL-10, IL-8, osteopontin, ICAM, VCAM, and NO3−/NO2− was determined." (PMID 30246778, 2018). "As expected, in the presence of 1 ng/ml TNFα, VCAM-1 expression was induced 300-fold compared to cells with no TNFα indicating significant endothelial dysfunction." (PMID 28500309, 2017). "Escin significantly ameliorated endothelial dysfunction (increased serum E-selectin and ICAM-1 and lung Wet/Dry ratio, decreased serum NO), and oxidative and inflammatory responses (increased serum MDA, MPO, IL-6 and TNF-α) (P < 0.05 or P < 0.01)." (PMID 28112272, 2017). "Levels of TNFα (inflammation) or ICAM-1 and VCAM-1 (endothelial dysfunction) are classically elevated in these conditions and may therefore alter LpPLA2 activity." (PMID 28974763, 2017). "In adiposity, excess secretion of various pro-inflammatory cytokines, chemokines, and proteases, such as TNF-α, IL-6, MCP-1, leptin, and PAI-1, by infiltrating macrophages and T cells around the adipose tissue, leads to endothelial dysfunction, oxidative stress, and inflammation activation." (PMID 28182687, 2017). "In fact, the present results revealed that MSC-CM did not contain TNF-α, which somewhat weakened the effects of thrombospondin-1 on endothelial dysfunction." (PMID 29152123, 2017). "Our data demonstrate that CD226 knockdown protects against TNF-α-induced stress fiber formation and cytoskeleton remodeling, indicating that inflammation-induced CD226 increases may aggravate endothelial dysfunction in diabetic hyperglycemia." (PMID 26910838, 2016). "Moreover, Pearson’s correlation coefficient revealed that endothelial dysfunction significantly correlated with aortic expression of inflammatory markers, TLR-4, TNF-α and IL-1β." (PMID 25826421, 2015).
endothelial dysfunction (continued). "Since IR promotes endothelial dysfunction, while anti-TNF-α treatment improves endothelial function in AS patients, our first objective was to evaluate short-term insulin response following anti-TNF-α infliximab therapy." (PMID 24757680, 2014). "This supports the hypothesis that post-COVID cardiac sequelae may be driven by non-classical inflammatory mechanisms, such as chemokine-mediated leukocyte retention or endothelial dysfunction, rather than sustained TNF-α signaling." (PMID 41472298, 2025). "Even in the absence of bacteremia, cytokine release (IL-6, TNF-α, IL-1β) may induce endothelial dysfunction, increased capillary permeability, and myocardial edema, which could suggest worsening of myocardial involvement by SIRS." (PMID 41466908, 2025). "Vascular injury, such as endothelial dysfunction and ischemia-reperfusion injury (IRI), disrupts tissue homeostasis and triggers the release of pro-inflammatory cytokines, including interferon (IFN) -γ, interleukin (IL)-1β, IL-6, and tumor necrosis factor (TNF)-α." (PMID 41188991, 2025). "Preclinical studies have shown that metformin regulates endotoxemia-induced endothelial dysfunction and inflammation through the AMPK/KLF2 axis, restoring KLF2 levels reduced by LPS and TNF-α stimulation, and inhibiting VCAM1 expression while reducing inflammatory factors like TNF-α and IL-6." (PMID 41373858, 2025). "Mechanically, IR-related markers could increase endothelial dysfunction by activating NF-κB or PI3K/Akt signaling pathways, increasing reactive oxygen species (ROS) production, and secreting proinflammatory cytokines (TNF-α, IL-6, IL-1β), to further improve cardiovascular disease risk." (PMID 41450551, 2025). "Endocan could be up-regulated in the presence of tumor necrosis factor-α (TNF-α)-, interleukin-1 (IL-1)-, and vascular endothelial growth factor (VEGF)-mediated pathways, which are all key players in the development of inflammation and endothelial dysfunction." (PMID 40282868, 2025). "Periodontal disease can lead to elevated levels of inflammatory markers such as C-reactive protein (CRP), interleukin-6 (IL-6), and tumor necrosis factor-alpha (TNF-α), which may contribute to endothelial dysfunction and impaired placental blood flow, thereby increasing the risk of pre-eclampsia." (PMID 39401230, 2024). "In addition, the inflammation in RA upregulates cytokines, such as tumor necrosis factor-alpha (TNF-α) and interleukin 1 beta (IL-1β), in affected joints that can impact distant sites, create oxidative stress, endothelial dysfunction, plaque instability, and thrombosis." (PMID 38340224, 2024). "For example, saxagliptin attenuates ox-LDL-induced cytokine and vascular adhesion molecule (TNF-α, Il-1β, ICAM-1, VCAM-1) production by inhibiting AP-1 and NF-κB and reduces Nox4 expression, thereby inhibiting the excessive generation of ROS and improving endothelial dysfunction." (PMID 37660030, 2023). "Furthermore, IFN- γ, TNFα, and IL-6 have been shown to induce hypoxia which promotes endothelial dysfunction; however, the mechanisms are not fully established." (PMID 37937252, 2023). "TNF-α induces migration and proliferation of smooth muscle cells from the medial side of the vessel wall to the intima through upregulation of intercellular cell adhesion molecule-1 (ICAM-1), scavenger receptor class A and MCP-1 expression, ultimately leading to endothelial dysfunction." (PMID 37822930, 2023). "However, in the current study, we observed no changes in the expression of ET-1, VCAM1, or ICAM1 in TNFα induced endothelial dysfunction in HUVECs when treated with 10 mU/mL of insulin for 24 h." (PMID 37893034, 2023). "The aim of our study was to find out whether endothelial dysfunction is associated with the number of CD34+ cells and TNF-α levels in patients with ischemic and non-ischemic HF after stimulation with granulocyte colony-stimulating factor (G-CSF)." (PMID 36005445, 2022).
endothelial dysfunction (continued). "High glucose could increase the expression of endothelial dysfunction markers of VCAM-1, TNF-α, and VEGF-A, thus leading to the dysfunction of vascular endothelial cells in terms of tube formation, migration, and proliferation and pathological changes in the placental vascular structure." (PMID 36448064, 2022). "In addition, as statins are studied well and proven to attenuate endothelial dysfunction via KLF2 activation, we then performed KLF2 promoter luciferase assays in COS-7 cells and TNFα-induced monocyte adhesion assays to compare the effects of statins (Simvastatin and Atorvastatin) with TSD." (PMID 36362263, 2022). "Finally, molecular US of αvβ3 integrins confirms the absence of endothelial dysfunction; the latter is provocable by TNF‐α." (PMID 35119216, 2022). "Notably, TNF-α is a proatherogenic cytokine because blockade of TNF-α with biological therapy (infliximab, adalimumab) diminished severity of UC or CD and enhanced the endothelial dysfunction in IBD patients." (PMID 35892915, 2022). "They suggested multiple inflammatory mediators such as tumor necrosis factor (TNF), caspase-1, IL-1β, and NOD-like receptor family pyrin domain containing 3 (NLRP3) inflammasome are produced during inflammaging, thereby resulting in BBB leakage and endothelial dysfunction." (PMID 36034144, 2022). "The aim of our study was to find out whether endothelial dysfunction is associated with the number of CD34+ cells and TNF-α levels in patients with advanced HF of ischemic and non-ischemic origin after stimulation with G-CSF." (PMID 36005445, 2022). "Chronic state of inflammation may also lead to increased secretion of proinflammatory cytokines such as interleukine (IL-6, IL-8), tumor necrosis factor alpha (TNF-α), interferon-γ (INF- γ), and monocyte chemoattractant protein 1 (MCP-1) which are involved in endothelial dysfunction." (PMID 35178447, 2022). "Thus, the present results also show that by its anti-inflammatory effect and inhibition of NF-kB and TNFα expression, EWH may improve endothelial dysfunction in arteries of DOCA-salt rats." (PMID 36139783, 2022). "Common inflammatory markers seen in endothelial dysfunction including C-reactive protein (CRP), IL-6, interferon gamma-induced protein-10 (IP-10), monocyte chemoattractant protein-1 (MCP-1), macrophage inflammatory protein-1 alpha (M1P1A), and TNF-α were also elevated in patients with COVID-19." (PMID 34012410, 2021). "Anisomycin, PMA, and TNF-α activated p38 MAPK and phosphorylated CREB and we hypothesized that MSK1/2 kinases may be involved in the development of endothelial dysfunction." (PMID 34445361, 2021). "Moreover, TREM-1 activation was shown to result in a persistent release of cytokines and chemokines (tumour necrosis factor alfa [TNF-α], IL-1β, IL-8, and monocyte chemotactic protein [MCP]-1), and is directly related to endothelial dysfunction and platelet activation." (PMID 34195785, 2021). "TNF-α levels can be two to three times higher in PreE than in normotensive pregnancies and have been linked to gestational HTN, endothelial dysfunction, and poor obstetric outcomes." (PMID 35096797, 2021). "Many cytokines such as TNF-alpha, IL-1, IL-2, IL-4, IL-6, IL-18, monocyte chemoattractant protein-1 (MCP-1), vimentin, and platelet-derived growth factor (PDGF) are produced by macrophages and T lymphocytes activated due to endothelial dysfunction and oxidative stress." (PMID 34349888, 2021). "The mechanism through which cytokines such as TNF might mediate endothelial dysfunction are not clear, though changes in the integrity of inter-endothelial cell junctions is a possible cause." (PMID 34659208, 2021). "Not surprisingly, it has been shown that DHA reduces TNF-α-induced endothelial cell injury by inhibiting gene expression related to endothelial dysfunction, such as plasminogen activator inhibitor 1 (SERPINE1/PAI-1) and lectin-like oxidized low-density lipoprotein receptor-1 (LOX1)." (PMID 32878052, 2020).
endothelial dysfunction (continued). "HUVECs were treated in the absence or presence of (i) TNF-α (100 ng/mL), (ii) sera from normal pregnancies (20%), or (iii) sera from preeclamptic women (20%) in the presence or absence of hydroxychloroquine (1 μg/mL) to assess endothelial dysfunction." (PMID 32260307, 2020). "Proinflammatory cytokines such as tumor necrosis factor-α (TNF-α) and interleukin-6 (IL-6) and hypoxia-inducible factor (HIF), reactive oxygen species and angiotensin II type 1 receptor, all are involved in the development of the endothelial dysfunction and preeclampsia." (PMID 31737362, 2019). "Finally, these data should be investigated together with the evaluation of direct markers of liver inflammation and fibrosis (such as TNF-alpha, TGF-beta and collagenase) in order to find any supposed direct correlation between endothelial dysfunction and liver disease progression." (PMID 28264657, 2017). "During RA, the increased expression of TNF-α, IL-1β, IL-6, adhesion molecules, angiotensin II type 1 receptor, and endothelin, together with a lower expression of NO, might contribute to SAH via endothelial dysfunction." (PMID 28103312, 2017). "The present study was therefore designed to evaluate whether or not GXSTC could protect against TNF-α-induced endothelial dysfunction." (PMID 25120637, 2014). "However, the precise mechanisms by which propofol attenuates TNF-α induced oxidative stress and endothelial dysfunction are not clear." (PMID 24396568, 2013). "With respect to TNF-α blockers, infliximab may improve endothelial function in RA after 12 weeks of therapy, suggesting that inflammation is a mediator of endothelial dysfunction, although such beneficial effects do not appear to sustain for a long time." (PMID 18325087, 2008). "Furthermore, TMAO contributes to atherosclerosis and endothelial dysfunction by promoting macrophage cholesterol accumulation and activating pro-inflammatory pathways such as NF-κB and MAPK, which lead to increased expression of adhesion molecules and cytokines (IL-1β, IL-18, TNF-α)." (PMID 41516081, 2025). "In the PVAT, at the earliest time point assessed i.e., 6 h.p.i and prior to endothelial dysfunction there was a significant but small elevation in CD69 and IFN-γ but no change in TNF-α, IL-6, or NOX2." (PMID 35930608, 2022). "We further found that, although inducing endothelial cell dysfunction with TNFα or placental factors were associated with rising VCAM-1, when GATA2 was silenced in healthy cells, VCAM-1 was down regulated suggesting GATA2 may not be causal of endothelial dysfunction." (PMID 30659233, 2019). "Biomarkers of endothelial dysfunction and low-grade inflammation were not modified (CRP, serum amyloid A, IL-6, IL-8, TNF-α, and soluble intercellular adhesion molecule-1) and neither was FMD." (PMID 31068933, 2019). "With respect to IBD, there is a lack of data in literature about the effects of anti-TNF-α and CVD in IBD patients and about endothelial dysfunction and the role of anti-TNF-α regarding this field." (PMID 29849875, 2018). "Probably the most relevant finding of our study was that, in absence of clear vascular remodelling or vasodilatadory endothelial dysfunction, increased levels of endothelium-release biomarkers (sVCAM-1, hs-CRP and TNF-α) were observed in patients with FD." (PMID 24207059, 2013). "Clearly, in the absence of TNF-α or at low TNF-α concentration, the endothelial dysfunction and THP-1 cell adhesion may be mediated by other pro-inflammatory cytokines released by activated monocytes or macrophages." (PMID 25811595, 2015). "The lack of correlation between TNFα levels and FMD might surprise, given the relevant contribution of this cytokine to the pathogenesis of endothelial dysfunction." (PMID 22938533, 2012). "However, whether the deleterious effects of miR-21 on endothelial dysfunction are through mediating DDAH1/ADMA/NO signal pathway, especially under the inflammatory cytokine TNF-α, is still not unclear." (PMID 29682517, 2018).
Stroke (941 papers, 2006 to 2026). Sudden impairment of blood flow to a part of the brain due to occlusion or rupture of an artery to the brain. "Key cytokines such as IL-6, IL-1β, TNF-α, and chemokines like IL-8 are rapidly released after stroke onset and are strongly associated with infarct size, neurological deterioration, and poor functional recovery." (PMID 40869247, 2025). "Clinically, elevated serum levels of interleukin-1β (IL-1β), interleukin-6 (IL-6), and tumor necrosis factor-α (TNF-α) at hospital admission correlate with significantly higher PSD risk in stroke patients." (PMID 41164411, 2025). "Particularly, elevated IL-6 and TNF-α levels have been independently associated with worse functional outcomes in stroke patients, even in the presence of technically successful thrombectomy." (PMID 41195016, 2025). "Elevated levels of TNF-alpha post-stroke have been consistently associated with unfavorable clinical outcomes, emphasizing its potential as a target for therapeutic intervention." (PMID 39859987, 2025). "Elevated TNF-α levels have been correlated with poor cardiovascular outcomes, including increased risk of myocardial infarction (MI), stroke, and heart failure [1224–1226]." (PMID 40407975, 2025). "In patients treated with TNF-α inhibitors, we observed an increased risk of MI but a decreased risk of stroke, particularly in high CV-risk individuals." (PMID 41007780, 2025). "While biologic therapies, including tumor necrosis factor (TNF)-alpha inhibitors, are effective in reducing systemic inflammation, their impact on mitigating stroke risk remains inconclusive." (PMID 40125129, 2025). "Although limited literature has documented the associations between IL-13RA2 and stroke, it is generally understood that IL-13RA2 can be upregulated by pro-inflammatory factors such as TNF-α and IL-1β." (PMID 40474979, 2025). "The findings indicate that treatment with TNF-α inhibitors (i.e., adalimumab, etanercept, infliximab) reduced the risk of stroke and transient ischemic attack by almost 50%, compared to treatment with methotrexate." (PMID 40584532, 2025). "Brain ischemic injury caused by stroke leads to systemic inflammatory responses and the production of various inflammatory mediators such as TNF‐α, IL‐6, and IL‐1β, which are also involved in the neuroinflammatory mechanisms of PSD." (PMID 38376033, 2024). "Microglial polarization is triggered by DAMPs and IFNγ stimulation, which activate the NF-kB and STAT1 pathways, similar to macrophages, resulting in the release of cytokines including IL-1β and TNF-α that cause neuronal death following stroke." (PMID 39062789, 2024). "Higher TNF-α and IL-6 levels in HbSS compared to HbAA are linked to increased vaso-occlusive crises and stroke risk." (PMID 39749215, 2024). "Identifying DADA2 is paramount for neurologists because the start of anti-TNF monoclonal antibodies is associated with reduction of the stroke recurrence, control of systemic inflammation and prevention of additional relapses." (PMID 38632524, 2024). "Within 6 to 12 h after cerebral ischaemia, the levels of TNF-α, IL-1β and IL-6 are increased in stroke patients and are associated with more severe neurological symptoms and poorer outcomes." (PMID 39198723, 2024). "Elevated levels of IL-1β, IL-6, and TNF-α are closely associated with stroke occurrence, while some lipid-lowering drugs, such as statins, have been shown to reduce stroke risk through their anti-inflammatory effects." (PMID 38659020, 2024). "Specifically, among studies focusing on myocardial infarctions or strokes as outcomes, the use of TNF-alpha inhibitors was associated with a 41% relative risk reduction in myocardial infarctions and a 43% reduction in strokes." (PMID 38294723, 2024). "H. pylori also increases the production of inflammatory mediators such as IL-6 and TNF-α, contributing to systemic inflammation and the risk of stroke." (PMID 39202269, 2024).